BEND4 (BEN domain containing 4)
Synonyms: CCDC4; FLJ35632; FLJ43965
Tractability: PROTAC: ubiquitination databases record sites on it.
Gene: Protein-coding gene on chromosome 4 (42,110,853 to 42,152,878, reverse strand). Ensembl gene ENSG00000188848.
Subcellular location (Human Protein Atlas): Nucleoli fibrillar center; Cytosol; Nucleoplasm
Gene Ontology:
Molecular function: DNA binding
Genetic constraint (gnomAD): Loss-of-function variants: 24 observed, 44.64 expected, observed/expected ratio (o/e) 0.54, 90% interval 0.39 to 0.76. The synonymous counts are far from expectation, so gnomAD's model fits this gene poorly and the ratio says little. Missense variants: 686 observed, 614.4 expected, observed/expected ratio (o/e) 1.12, 90% interval 1.05 to 1.19. Synonymous variants: 320 observed, 261.2 expected, observed/expected ratio (o/e) 1.23, 90% interval 1.12 to 1.34.
Homologues: Orthologues: macaque BEND4 (99% identical), mouse Bend4 (90% identical), rat Bend4 (90% identical), dog BEND4 (89% identical), guinea pig BEND4 (81% identical), chimpanzee BEND4 (81% identical), pig BEND4 (76% identical), tropical clawed frog bend4 (72% identical), rabbit BEND4 (67% identical), zebrafish BEND4 (56% identical).
Diseases named in the same sentence as BEND4 in open-access papers:
BEND4 is named in the same sentence as 5 diseases in open-access papers, as found by Europe PMC text mining. Sharing a sentence is not in itself a finding about the gene and the disease. The quoted sentences say what the papers report.
Acute encephalopathy (1 paper, 2024). "The murine lncRNA Bendr (also referred to as linc1536 locus,) stands for Bend4 regulation not dependent on RNA, and its target gene is Bend4, which in humans has been found to be related to infection-induced acute encephalopathy." (PMID 39123456, 2024).
type 1 diabetes (1 paper, 2014). "For example, we found that rs11171739, which is associated to type 1 diabetes, is a trans-eQTL of DCAF16, as previously shown in monocytes and is also a trans-eQTL of BEND4." (PMID 25010687, 2014).
BEND4 also shares sentences with these, for which no sentence is quoted: infection (1 paper); Myelodysplasia (1); neuroblastoma (1).